CD82 (CD82 molecule)
Description:
Structural component of specialized membrane microdomains known as tetraspanin-enriched microdomains (TERMs), which act as platforms for receptor clustering and signaling. Participates thereby in diverse biological functions such as cell signal transduction, adhesion, migration and protein trafficking. Acts as a attenuator of EGF signaling, facilitating ligand-induced endocytosis of the receptor and its subsequent desensitization. Mechanistically, modulates ligand-induced ubiquitination and trafficking of EGFR via E3 ligase CBL phosphorylation by PKC. Increases cell-matrix adhesion by regulating the membrane organization of integrin alpha4/ITA4. Modulates adhesion and suppresses cell migration through other integrins such as the alpha6/ITGA6 and beta1/ITGB1. Decreases cell-associated plasminogen activation by interfering with the interaction between urokinase-type plasminogen activator/PLAU and its receptor PLAUR. Associates with CD4 or CD8 and delivers costimulatory signals for the TCR/CD3 pathway. Plays a role in TLR9 trafficking to acidified CpG-containing compartments by controlling interaction between TLR9 and VAMP3 and subsequent myddosome assembly (By similarity). Inhibits LPS-induced inflammatory response by preventing binding of LPS to TLR4 on the cell surface. Plays a role in the activation of macrophages into anti-inflammatory phenotypes (By similarity). Independently of Toll-like receptor (TLR) signaling, is recruited to pathogen-containing phagosomes prior to fusion with lysosomes and thereby participates in antigen presentation (By similarity). Also acts to control angiogenesis and switch angiogenic milieu to quiescent state by binding and sequestering VEGFA and PDGFB to inhibit the signaling they trigger via their respective cell surface receptor.
Synonyms: KAI1; SAR2; ST6; TSPAN27; R2; IA4; 4F9; C33; GR15
Tractability: Antibody: UniProt places it where antibodies can reach, with high confidence; its Gene Ontology location is reachable by antibodies, with high confidence; UniProt predicts a signal peptide or a membrane-spanning region. PROTAC: ubiquitination databases record sites on it; its protein half-life has been measured.
Gene: Protein-coding gene on chromosome 11 (44,564,414 to 44,620,924, forward strand). Ensembl gene ENSG00000085117.
Subcellular location: Cell membrane; Cytoplasmic vesicle, phagosome
Subcellular location (Human Protein Atlas): Vesicles
Gene Ontology:
Molecular function: protein binding
Cellular component: extracellular exosome; plasma membrane; membrane; phagocytic vesicle
Genetic constraint (gnomAD): Loss-of-function variants: 29 observed, 32.38 expected, observed/expected ratio (o/e) 0.9, 90% interval 0.67 to 1.22. The upper end of that interval is the gene's LOEUF score, 1.22, which puts it in group 5 of 6, group 1 being the genes least tolerant of losing a copy. Missense variants: 320 observed, 327.22 expected, observed/expected ratio (o/e) 0.98, 90% interval 0.89 to 1.07. Synonymous variants: 150 observed, 131.56 expected, observed/expected ratio (o/e) 1.14, 90% interval 1 to 1.31.
Homologues: Orthologues: chimpanzee CD82 (99% identical), guinea pig CD82 (77% identical), mouse Cd82 (76% identical), rat Cd82 (76% identical), dog CD82 (75% identical), pig CD82 (73% identical), macaque CD82 (72% identical), rabbit CD82 (71% identical), tropical clawed frog cd82 (55% identical), zebrafish cd82b (54% identical), zebrafish cd82a (51% identical). Paralogues in human: CD37 (38% identical), TSPAN5 (28% identical), TSPAN9 (28% identical), CD53 (28% identical), TSPAN8 (27% identical), TSPAN1 (27% identical), TSPAN11 (26% identical), TSPAN4 (26% identical), CD151 (26% identical), TSPAN17 (25% identical), TSPAN19 (25% identical), TSPAN10 (24% identical), and 20 more.
Diseases named in the same sentence as CD82 in open-access papers:
CD82 is named in the same sentence as 135 diseases in open-access papers, as found by Europe PMC text mining. Sharing a sentence is not in itself a finding about the gene and the disease. The quoted sentences say what the papers report.
prostate carcinoma (63 papers, 2002 to 2025). A carcinoma that arises from epithelial cells of the prostate gland. "Downregulation of TSPAN27 (CD82) is strongly associated with poor outcomes of prostate cancer, colon cancer, cervical cancer, and ovarian cancer." (PMID 29650964, 2018). "Taken together, the current data suggest that high CD82 expression blocks fibronectin adhesion-induced EMT in prostate cancer cells through the repression of associated α3β1/α5β1 integrin-mediated signaling events." (PMID 27926483, 2017). "Since CD82 associates with fibronectin-binding integrins physically and functionally, we cultured the prostate cancer cells on fibronectin-coated plates and examined cell morphology." (PMID 27926483, 2017). "Downregulation of KAI1/CD82 is associated with the acquisition of high metastatic properties in Dunning rat prostate cancers." (PMID 23420768, 2013). "Our study indicated that loss or reduction of CD82 in prostate cancer enhanced E-cadherin shedding from membrane, which might decrease the stabilization of E-cadherin/β-catenin complex." (PMID 33204367, 2020). "We have identified multiple gene targets that could further be explored, including their association with CD82 in regulating prostate cancer metastasis." (PMID 33298014, 2020). "Moreover, decrease or loss of CD82 expression is closely associated with malignancy and poor prognosis in many human cancers including prostate cancer." (PMID 27926483, 2017). "Furthermore, PC3 cells were found to be deficient in CD82 protein, indicating that CD82 was downregulated in all three human prostate cancer cell lines examined." (PMID 27926483, 2017). "Notably, the EMT degrees in those parental cell lines, as well as the stable transfectant clones with different CD82 levels, appeared to be inversely correlated with CD82 expression levels, implicating that decrease or loss of CD82 expression renders prostate cancer cells prone to undergoing EMT." (PMID 27926483, 2017). "The CD82 protein has the function of inhibiting tumor metastasis and thus is a therapeutic target in prostate cancer cells." (PMID 41155703, 2025). "When CD82 was overexpressed in Du145 prostate cancer cells, the cell surface expression of integrin α6 decreased and the cellular morphogenesis process on Matrigel was abolished." (PMID 39361713, 2024). "determined that CD82 can interact with the α3β1/α5β1 integrins in prostate cancer cells, ultimately impairing EMT induction by inhibiting FAK/Src signaling." (PMID 35280793, 2022). "It associates with transmembrane protein KAI1/CD82, which negatively regulates the metastasis potential of prostate cancer." (PMID 33605506, 2021). "CD82 was first discovered to be under-expressed in cell lines derived from metastatic prostate cancer cells in 1995." (PMID 34503296, 2021). "Kangai 1 (KAI1/CD82) is another human MSP identified in prostate cancer cells, and the expression of KAI1 in prostate cancer cells was shown to inhibit the progression of lung cancer." (PMID 33753879, 2021). "CD82 expression has also been reported in other cancer types, which include cancers of the prostate, lung and pancreas." (PMID 34503296, 2021). "The tetraspanin CD82 (also known as KAI-1) has been identified as a metastasis suppressor in prostate cancer." (PMID 34445169, 2021). "Here, we identified a novel function of CD82 on posttranslational regulating E-cadherin in prostate cancer." (PMID 33204367, 2020). "Further study proved that a disintegrin and metalloproteinase ADAM17 as an executor of E-cadherin cleavage mediated the inhibitory regulation of CD82 in E-cadherin shedding in prostate cancer." (PMID 33204367, 2020). "Functionally, CD82 inhibited cell migration and E-cadherin cleavage from the cell membrane in prostate cancer cell." (PMID 33204367, 2020).
prostate carcinoma (continued). "CD82 expressions were obviously decreased in prostate cancer cells (LNCaP, C4-2, C4-2B, PC-3, DU145, and CWR22Rv1) compared with prostate normal epithelia cell RWPE-1 and benign prostatic hyperplasia cell BPH-1 by real-time PCR and Western blot." (PMID 33204367, 2020). "The decreased expression of CD82 was detected in prostate cancer tissue by immunohistochemical assay compared with the matched adjacent normal tissue." (PMID 33204367, 2020). "It provided a potential mechanism contributing to the metastasis of prostate cancer and a novel function of CD82 as a metastatic suppressor." (PMID 33204367, 2020). "In our study, the declined expression of CD82 was verified in prostate cancer tissues and cell lines compared with normal tissue and cell lines." (PMID 33204367, 2020). "KAI1, which is identical to CD82, was initially identified as a metastasis suppressor of prostate cancer." (PMID 27926483, 2017). "Recent years studies have demonstrated CD82 as a metastatic suppressor in many malignant solid cancer cell types including prostate cancer,bladder cancer, breast cancer, pancreatic cancer, and hepatocarcinoma cells." (PMID 28881668, 2017). "Previously, we also found that CD82 suppresses β1 integrin activation by matrix adhesion and formation of a focal adhesion complex in prostate cancer cells, along with a decreased expression of fibronectin." (PMID 27926483, 2017). "A wound-closure cell migration assay also revealed that CD82 inhibits the chemostatic motility of prostate cancer cells." (PMID 27926483, 2017). "We first examined CD82 expression levels in three prostate cancer cell lines derived from metastatic sites in prostate cancer patients, LNCaP from a lymph node metastasis, DU145 from a bone metastasis, and PC3 from a brain metastasis." (PMID 27926483, 2017). "Previously, we have found that CD82 not only suppresses fibronectin expression but also the activation of β1 integrins and their downstream signaling in prostate cancer cells." (PMID 27926483, 2017). "Taken together, these findings suggest that CD82 is co-downregulated with E-cadherin during malignant prostate cancer development, which provokes prostate tumor cells to undergo EMT." (PMID 27926483, 2017). "An in vivo invasion assay using chick embryos also illustrated that high CD82 expression significantly suppressed the invasive capacities of prostate cancer cells." (PMID 27926483, 2017). "KAI1, also named as CD82, which is originally considered as a suppressor gene of metastasis in prostate cancer cells." (PMID 28431527, 2017). "In the present study, we found that high CD82 expression suppresses development of a motile mesenchymal phenotype and rather intensifies epithelial characteristics in human prostate cancer cells adhered to the fibronectin matrix." (PMID 27926483, 2017). "KAI1/CD82 was originally identified as a suppressor of metastasis located on human chromosome 11p11.2 in prostate carcinoma." (PMID 26408312, 2015). "The KAI1/CD82 gene was originally identified as a suppressor of metastasis of tumor in prostate carcinoma." (PMID 24758564, 2014). "Decreased KAI1/CD82 expression has been observed to correlate with metastasis and poor prognosis in many human solid tumors, such as prostate cancer, lung cancer, breast cancer, colon cancer, gastric cancer, liver cancer, and kidney cancer." (PMID 24758564, 2014). "The same alterations in morphology were also observed in the PC3 prostate cancer cells in which KAI1/CD82 was overexpressed." (PMID 23251627, 2012). "KAI1 (CD82) was first identified as a prostate cancer metastasis suppressor through genetic screening." (PMID 22390300, 2012).
prostate carcinoma (continued). "For example, the metastasis suppressor gene KAI1/CD82 downregulates fibronectin expression and β1 integrin activation in prostate cancer cells, thus inhibiting the ability of tumor cells to interact with niche components." (PMID 22699312, 2012). "The purpose of this study was to establish the precise mechanism by which KAI1 (CD82), a metastasis-suppressor gene initially discovered in prostate cancer, inhibits Src and affects the metastasis of prostate carcinoma." (PMID 22390300, 2012). "KAI1/CD82 is considered to be a metastasis-suppressor gene of prostate cancer and low KAI1/CD82 expression has been reported to be involved in the malignant progression of prostate cancer." (PMID 12838318, 2003). "Anti-cancer 1 (KAI1), commonly referred to as CD82, has emerged as a pivotal tumor metastasis suppressor gene in recent research endeavors, initially recognized for its specific role in inhibiting metastasis in prostate cancer cells." (PMID 41239615, 2025). "Mechanistically, Wnt/β-catenin signaling has been reported to down-regulate the metastasis suppressor gene kangai 1 (KAI1, also known as CD82) in prostate cancer cells to potentially facilitate metastatic progression, and KAI1 expression is frequently decreased in metastatic prostate cancer." (PMID 35204808, 2022). "Because it had a direct association with several exosome markers, such as CD9, CD81 and CD82, we carried out exosome extraction and analysis for the prostate cancer cell lines PC3 and Du145 cells with EWI‐2 CRISPR/Cas9 knockout as well as the overexpression of EWI‐2 in PC3 cells." (PMID 33605506, 2021). "KAI1/CD82 gene was initially cloned as a human gene that could inhibit the metastatic ability of rat AT6.1 prostate cancer cells." (PMID 34306081, 2021). "Thus, studying these profiles and identifying the genes involved in these cells will help us better understand CD82’s role as a tumor metastasis suppressor in prostate cancer." (PMID 33298014, 2020). "This interesting data implied that the activity of ADAM17 may be mostly blocked by CD82 in prostate cancer cells." (PMID 33204367, 2020). "Taken together, the present data demonstrate a CD82 function of the suppression of fibronectin-induced EMT in prostate cancer cells, which may account for the invasion-suppressing role of CD82." (PMID 27926483, 2017). "Immunofluorescence staining of human prostate cancer tissue specimens illustrated a negative association of CD82 with EMT-related gene expression as well as prostate malignancy." (PMID 27926483, 2017). "However, high CD82 expression rendered prostate cancer cells to have intensified epithelial characteristics upon fibronectin engagement, along with decreased cell motility and invasiveness." (PMID 27926483, 2017). "Furthermore, the present study defines the expression level of CD82 as a crucial factor to determine how the fibronectin matrix influences the epithelial/mesenchymal state of prostate cancer cells." (PMID 27926483, 2017). "Thus, high CD82 expression inhibits prostate cancer cells adhered to the fibronectin matrix from developing a fibroblast-like mesenchymal morphology." (PMID 27926483, 2017). "Altogether, these results suggest that CD82 suppresses EMT in prostate cancer cells adhered to the fibronectin matrix by repressing adhesion signaling through lateral interactions with the associated α3β1 and α5β1 integrins, leading to reduced cell migration and invasive capacities." (PMID 27926483, 2017). "Du145 prostate cancer cells barely express any endogenous KAI1/CD82." (PMID 23251627, 2012). "Furthermore, EWI2/PGRL, an immunoglobulin superfamily member, could synergize KAI1/CD82 to inhibit the migration of prostate cancer cells." (PMID 34306081, 2021).
prostate carcinoma (continued). "A recent study suggests that CD82 may suppress epithelial to mesenchymal transition (EMT) in prostate cancer cells on fibronectin matrix by laterally interacting with α3β1 and α5β1 integrins to repress integrin signaling, inhibiting cell migration and invasion." (PMID 33298014, 2020). "However, if CD82 is downregulated below a certain level during malignant progression, fibronectin matrix can activate its receptor integrins so that prostate cancer cells receive strong enough adhesion signals to induce EMT, resulting in the development of a motile mesenchymal phenotype." (PMID 27926483, 2017). "High expression of FGF13 in metastatic prostate -CD82 cells observed in our study indicates a potential interaction between FGF13 and CD82 to promote metastasis in prostate cancer." (PMID 33298014, 2020). "Although CD82 was expressed in LNCaP and DU145 cells, CD82 protein levels in these two prostate cancer cell lines were significantly lower than those in a human prostate epithelial cell line, PZ-HPV-7." (PMID 27926483, 2017). "Using the DU145 prostate cancer cell model, over-expression of KAI1/CD82 induced homotypic cell-cell aggregation." (PMID 26431493, 2015). "Using DU145 metastatic prostate cancer cells as the experimental model, it was demonstrated that inhibition of the p130Cas-CrkII pathway is crucial for the KAI1/CD82-mediated suppression of cell motility in DU145 cells." (PMID 26431493, 2015). "In the prostate cancer cell lines, DU145 and PC3, KAI1/CD82 reduced both integrin-dependent and HGF-induced activation of c-Met, subsequently inhibiting signaling to activate Src, resulting in reduced activation of p130Cas." (PMID 26431493, 2015). "In Du145 prostate cancer cells, KAI1/CD82 expression abolished the lamellipodia formation on FN-coated plates or regular cell culture flask." (PMID 23251627, 2012). "In PC3 prostate cancer cells, KAI1/CD82 inhibited lamellipodia formation extensively on FN but partially on LN." (PMID 23251627, 2012). "Another study further revealed that CD82 enhanced the shedding of E-cadherin through the suppression of disintegrin and metalloprotease 17 (ADAM17), while promoting motility, migratory, and invasive properties of prostate cancer cells." (PMID 34503296, 2021). "Another result pointed out that KAI1/CD82 suppressed adhesion signaling pathways through lateral interactions with α3β1 and α5β1 integrin, thereby inhibiting EMT adhesion of prostate cancer cells to fibronectin matrix and reducing cell migration and invasion ability." (PMID 34306081, 2021). "CXCL14, as a fibroblast autocrine growth factor can act as a prostate cancer stimulator and high CXCL14 gene expression in -CD82 cells may indicate a possible link between CXCL14 and CD82 in the tumorigenesis of prostate cancer." (PMID 33298014, 2020). "The significantly upregulated genes in -CD82 cells such as CXCL14 and FGF13 could potentially serve as biomarkers or therapeutic targets for diagnosis and treatment of prostate cancer." (PMID 33298014, 2020). "In addition, the mechanism underlying the anti-adhesion effect of metastatic suppressor KAI1/CD82 is that overexpressing KAI1/CD82 results in a reduced FN expression, leading to an attenuation of the matrix adhesion of human prostate cancer cells." (PMID 31861892, 2019). "To confirm whether CD82 inhibition of fibronectin-mediated EMT is dependent on fibronectin-receptor signaling events, we overexpressed wild-type FAK and ILK in prostate cancer cells through gene transfection." (PMID 27926483, 2017). "Enforced expression of CD82/KAI1 by gene transfection significantly reduced lung metastases of rat prostate cancer cells, without affecting primary tumor growth." (PMID 27926483, 2017). "Here, we found that a fibronectin matrix induced mesenchymal phenotypes in human prostate cancer cells with no or low CD82 expression levels." (PMID 27926483, 2017).